TRDMT1 (tRNA aspartic acid methyltransferase 1)
Diseases named in the same sentence as TRDMT1 in open-access papers (continued):
Sharing a sentence is not in itself a finding about the gene and the disease.
cancer (56 papers, 2013 to 2026). A tumor composed of atypical neoplastic, often pleomorphic cells that invade other tissues. "Studies have shown that TRDMT1 dysfunction is closely associated with the development of various diseases, including metabolic disorders, viral infections, and certain types of cancer." (PMID 40984038, 2025). "Additionally, alterations in DNA methyltransferase 2/tRNA aspartic acid methyltransferase 1 (DNMT2/TRDMT1) have been linked to cancer and drug resistance." (PMID 38476632, 2024). "We conclude that DNMT2/TRDMT1 gene knockout, at least in selected cellular cancer models, affects adaptive responses associated with protein homeostasis networks that during prolonged ER stress may result in increased sensitivity to apoptotic cell death." (PMID 36273376, 2023). "It was suggested that DNMT2/TRDMT1 might be considered as a novel target in cancer therapy as the loss of DNMT2/TRDMT1 sensitized cancer cells to PARP inhibitors in vitro and in vivo." (PMID 34139673, 2021). "It is reasonable to speculate that additional cancer mutations that stabilize TRDMT1 may also enhance the therapeutic response in cancers." (PMID 33778494, 2021). "Interestingly, G155V mutation of TRDMT1 leads to excessive TRDMT1 degradation, and subsequent loss of TRDMT1 function leads to inefficient repair and contributes to increased DNA damage sensitivity of cancer cells." (PMID 33778494, 2021). "Our data demonstrate that the loss of TRDMT1 expression in cancer could lead to increased sensitivity of cancer cells to chemotherapy and/or radiotherapy due to inefficient DNA repair." (PMID 33778494, 2021). "Loss of TRDMT1 in cancer cells confers sensitivity to PARP inhibitors in vitro and in vivo." (PMID 32503981, 2020). "Therefore, Alt-NHEJ may at least partially compensate for the loss of TC-HR in DSB repair upon TRDMT1 inhibition, contributing to the damage resistance of cancer cells." (PMID 37777505, 2023). "The deletion of DNMT2/TRDMT1 in cancer cells impaired the DOX-induced unfolded protein response and increased the susceptibility of cancer cells to endoplasmic reticulum stress-induced death." (PMID 39340806, 2024). "Our previous studies showed that TRDMT1-mediated RNA m5C modification promotes transcription coupled-homologous recombination (TC-HR) activity in cancer cells." (PMID 37777505, 2023). "G155 is a hotspot of somatic cancer mutations, which locates on the back side, right in front of motif VIII of TRDMT1." (PMID 33778494, 2021). "There is limited information on DNMT2/TRDMT1-mediated effects on cancer initiation, promotion, progression and therapy." (PMID 34139673, 2021). "Given the crucial role of TDRMT1 in the DNA damage response of cancer cells, we developed a potent inhibitor of TRDMT1 and showed that it sensitizes cancer cells to DNA-damaging agents, thereby opening a new avenue to targeting RNMTs in cancer therapy." (PMID 33778494, 2021). "Previous studies and our current findings suggested TRDMT1 is a promising target for cancer therapy based on its role in DNA repair." (PMID 33778494, 2021). "These new findings indicate an important role of TRDMT1 in cell survival after DNA damage, motivating us to investigate the function of TRDMT1-mediated RNA m5C modification in cancer therapy." (PMID 33778494, 2021). "The roles of TRDMT1 and m5C in HR are relevant to the sensitivity of cancer cells to radiotherapy and PARPi therapy." (PMID 32503981, 2020). "Bioinformatic and functional analysis revealed that lnc-TRDMT1-5 was involved in many crucial pathways in cancer, such as the PI3K/AKT and Wnt signaling pathways." (PMID 32547604, 2020). "TRDMT1 may be suggested as a novel modulator of gene expression by changes in DNA methylome that may affect cancer cell fates during chemotherapy." (PMID 37169948, 2023). "It is worthwhile to mention that DNMT2/TRDMT1 activity can be also pharmacologically inhibited as azacytidine (AZA) may diminish DNMT2/TRDMT1-mediated RNA methylation in human cancer cell lines." (PMID 34139673, 2021).
cancer (continued). "Importantly, depletion of TRDMT1 from tumors in mice increases their sensitivity to PARPi in vivo, showing that the function of m5C in HR is relevant to the use of PARPi in targeted cancer therapy." (PMID 32503981, 2020). "The TRDMT1–m5C axis discovered in this study extends the concept of DNA damage codes from post-translational modifications of proteins to post-transcriptional modifications of RNAs, providing exciting opportunities for targeted cancer therapy." (PMID 32503981, 2020). "While UHRF2 could not only interact with other Ub/UBL-related proteins that regulate Ub/UBL protein modification, it could also interact with PCNA, DNMT1, HDAC1, and TRDMT1, which participate in DNA replication, cell cycle progression, microRNAs in cancer, etc.." (PMID 38879525, 2024). "The RNA methyltransferase TRDMT1 has recently emerged as a key regulator of homologous recombination (HR) in the transcribed regions of the genome, but how it is regulated and its relevance in cancer remain unknown." (PMID 33778494, 2021). "The expression level of lnc-TRDMT1-5, a 706 bp non-coding transcript, was shown to be higher in BC tissues compared with adjacent normal tissues and in chemoresistant cancer cells compared with sensitive cells, indicating that it might be involved in cancer development and drug resistance." (PMID 32547604, 2020). "In 2022, it was discovered that FMRP serves as an m5C reader, acting as a coordinator between the m5C writer TRDMT1 and eraser ten-eleven translocation 1 (TET1), and this coordination facilitates mRNA-dependent repair and cell survival in cancer." (PMID 39340806, 2024). "Simultaneous disruption of TC-HR and alt-NHEJ with TRDMT1 inhibitor and PARP or Polymerase θ (POLθ) inhibitor kills cancer cells synergistically, providing a promising strategy to enhance the efficacy of PARP, POLθ and TRDMT1 targeted therapies." (PMID 37777505, 2023). "According to this idea, one would predict that inhibition of both TRDMT1 and Alt-NHEJ should kill cancer cells more effectively." (PMID 37777505, 2023). "To evaluate its function in ATC drug resistance, we examined correlations between the expression of 12 m5C regulators [NSUN2-7, TRDMT1 (writers); ALKBH1, TET2, ALKBH3 (erasers); YBX1 and ALYREF (readers)] and drug sensitivity in the Cancer Therapeutics Response Portal (CTRP)." (PMID 40083919, 2025). "DNA methyltransferase 2/tRNA aspartic acid methyltransferase 1 (DNMT2/TRDMT1) may modulate a number of stress responses, cell proliferation and survival in normal and cancer cells." (PMID 36273376, 2023). "Additionally, we explored the correlation between IL18RAP and five methyltransferases (DNMT3L, DNMT3B, DNMT3A, TRDMT1, and DNMT1) across cancers." (PMID 37698530, 2023). "Detailed consequences of the lack of functional DNMT2/TRDMT1 gene during drug-mediated senescence in four human cancer cell lines are presented and discussed." (PMID 34139673, 2021). "DNMT2 or TRDMT1 and DNMT3L are yet to be studied in detail in the different cancers." (PMID 24822169, 2014). "Importantly, simultaneous disruption of both TC-HR and Alt-NHEJ with TRDMT1 and PARP or Polymerase θ inhibitors prevents alternative DSB repair and exhibits synergistic cytotoxic effects on cancer cells, suggesting an effective strategy to exploit genomic instability in cancer therapy." (PMID 37777505, 2023). "However, there are no data on TRDMT1-mediated changes in DNA methylome and related signaling pathways in cancer cells." (PMID 37169948, 2023). "However, the role of DNMT2/TRDMT1 during chemotherapy-induced senescence and related responses in cancer cells of different origin and type has not been addressed." (PMID 34139673, 2021). "In this context, the DNMT2 (TRDMT1) gene has not been considered, because human DNMT2 is an RNA methyltransferase and this study was primarily focused on genes coding for DNMTs, and because they have been reported to play an important role in the development of cancer." (PMID 23638630, 2013).
tumor (25 papers, 2009 to 2026). "Notably, on day 12 after the injection of tumor cells, PARPi reduced the growth of TRDMT1-depleted tumors more than control tumors (70% vs. 45%), suggesting that loss of TRDMT1 increases the HR deficiency in tumor cells." (PMID 32503981, 2020). "UMAP-based expression overlays revealed that NSUN2, YTHDC1, ALKBH5, ZC3H13, and TRDMT1 were predominantly expressed within epithelial clusters, consistent with a tumor-intrinsic regulatory role." (PMID 40565233, 2025). "TRDMT1 and ZC3H13 have also been implicated in modulating mRNA splicing and stability, suppressing tumor progression in urological cancers." (PMID 40565233, 2025). "MDA-MB-231 cells infected with lentiviruses (LV)-expressing TRDMT1 shRNA (shTRDMT1) or control shRNA (NC) were injected intraperitoneally into mice, and tumor growth was measured over 14 days." (PMID 32503981, 2020). "Clinically, TRDMT1 has emerged as a promising anticancer target, with recent studies identifying small‐molecule inhibitors that disrupt its m5C methylation activity and suppress tumour growth." (PMID 40984038, 2025). "These heterogeneous effects across age, sex, and tumour origin suggest that the penetrance of TRDMT1 SNPs may depend on host and tumour context, consistent with findings that genetic variant effects can vary across tissues or developmental states." (PMID 40984038, 2025). "A potent TRDMT1 inhibitor resensitizes TRDMT1-high tumor cells to cisplatin." (PMID 33778494, 2021). "In contrast, the expressions of NSUN3, NSUN4, NSUN7, TRDMT1, DNMT1, YBX1, and TET2 were low in tumors and had a tumor-suppressive effect." (PMID 36661693, 2022). "For example, knockdown of TRDMT1 can change the level of HEK293 mRNA methylation and inhibit tumour cell proliferation and migration." (PMID 33400376, 2021). "The results showed that the expression levels of seven tRNA-modifying genes (FTSJ1, ADAT1, U13, RNMTL1, TRDMT1, METTL14, and TRMT1L) in NSCLC tumor tissues were significantly lower than that in normal tissues (all P values < 0.05)." (PMID 32393790, 2020). "Furthermore, increased TRDMT1 expression is correlated with critical clinical features such as MYCN amplification and INSS staging, suggesting its role in tumour progression." (PMID 40984038, 2025). "In all 11 writers, the expression of TRDMT1 was low in both tumor and normal tissues, and its expression was not significantly different in tumor vs. normal tissues." (PMID 37907576, 2023). "To obtain a more comprehensive insight into the epigenetic control of tumor aggressiveness, we performed an RT-qPCR analysis of the DNA methyltransferases DNMT1, 3A, and 3B, the DNA demethylases TET1, 2, 3, and TDG, and the RNA methyltransferase TRDMT1 in relation to tumor metastasis and invasion." (PMID 37367043, 2023). "In the absence of PARPi, depletion of TRDMT1 (LV-shTRDMT1) also reduced tumor growth modestly." (PMID 32503981, 2020). "Similarly, ZC3H13 and TRDMT1, despite inclusion in multiple prognostic signatures (e.g., BLCA and CESC), showed moderate-to-low expression in fibroblasts and immune cells, supporting roles in stromal remodeling rather than direct tumor cell regulation." (PMID 40565233, 2025).
metabolic disorders (8 papers, 2019 to 2025). "Based on genetic factors, DNMT2/TRDMT1-dependent RNA modifications are important in determining the coding signature of sperm small non-coding RNA, which is required for paternal epigenetic memory and in the transmission of paternally acquired metabolic diseases to offspring." (PMID 35327610, 2022).
TRDMT1 also shares sentences with these, for which no sentence is quoted: infection (7 papers); cervical cancer (4); bacterial infection (2); hepatocellular carcinoma (2); lung carcinoma (2); malaria (2); microphthalmia (2); prostate carcinoma (2); renal carcinoma (2); small cell lung carcinoma (2); age (1); alcoholic hepatitis (1); anaplastic thyroid carcinoma (1); brain tumor (1); clear cell renal cell carcinoma (1); colon cancer (1); cyst (1); dengue (1); diabetes (1); diabetic nephropathy (1); E. coli infection (1); endocrine tumors (1); endometrial cancer (1); genetic disorders (1); heart failure (1); hypertrophy (1); Infertility (1); Insulin resistance (1); Insulinoma (1); liver cancer (1).
A further 15 diseases each share a sentence with TRDMT1 in 1 paper.